LIN7C (lin-7 cell polarity scaffold C)
Description:
Plays a role in establishing and maintaining the asymmetric distribution of channels and receptors at the plasma membrane of polarized cells. Forms membrane-associated multiprotein complexes that may regulate delivery and recycling of proteins to the correct membrane domains. The tripartite complex composed of LIN7 (LIN7A, LIN7B or LIN7C), CASK and APBA1 associates with the motor protein KIF17 to transport vesicles containing N-methyl-D-aspartate (NMDA) receptor subunit NR2B along microtubules (By similarity). This complex may have the potential to couple synaptic vesicle exocytosis to cell adhesion in brain. Ensures the proper localization of GRIN2B (subunit 2B of the NMDA receptor) to neuronal postsynaptic density and may function in localizing synaptic vesicles at synapses where it is recruited by beta-catenin and cadherin. Required to localize Kir2 channels, GABA transporter (SLC6A12) and EGFR/ERBB1, ERBB2, ERBB3 and ERBB4 to the basolateral membrane of epithelial cells.
Synonyms: Lin-7C; MALS-3; MALS3; VELI3; LIN-7-C; FLJ11215
Tractability: Antibody: UniProt places it where antibodies can reach, with high confidence; its Gene Ontology location is reachable by antibodies, with high confidence. PROTAC: ubiquitination databases record sites on it; its protein half-life has been measured.
Gene: Protein-coding gene on chromosome 11 (27,494,418 to 27,506,769, reverse strand). Ensembl gene ENSG00000148943.
Subcellular location: Cell membrane; Basolateral cell membrane; Cell junction; Postsynaptic density membrane; Cell junction, tight junction
Pathways (Reactome):
Neuronal System: Assembly and cell surface presentation of NMDA receptors; Dopamine Neurotransmitter Release Cycle; Neurexins and neuroligins
Gene Ontology:
Molecular function: cytoskeletal protein binding; L27 domain binding; protein binding; protein domain specific binding; protein-macromolecule adaptor activity; PDZ domain binding
Biological process: morphogenesis of an epithelial sheet; neurotransmitter secretion; protein transport; regulation of synaptic assembly at neuromuscular junction; synaptic vesicle transport
Cellular component: cell-cell junction; cytoplasm; MPP7-DLG1-LIN7 complex; plasma membrane; basolateral plasma membrane; membrane; synapse; anchoring junction; bicellular tight junction; glutamatergic synapse; postsynaptic density membrane; presynapse
Genetic constraint (gnomAD): Loss-of-function variants: 12 observed, 15.95 expected, observed/expected ratio (o/e) 0.75, 90% interval 0.48 to 1.22. The upper end of that interval is the gene's LOEUF score, 1.22, which puts it in group 5 of 6, group 1 being the genes least tolerant of losing a copy. Missense variants: 141 observed, 175.07 expected, observed/expected ratio (o/e) 0.81, 90% interval 0.7 to 0.93. Synonymous variants: 68 observed, 62.31 expected, observed/expected ratio (o/e) 1.09, 90% interval 0.9 to 1.34.
Homologues: Orthologues: chimpanzee LIN7C (100% identical), dog LIN7C (100% identical), mouse Lin7c (100% identical), guinea pig LIN7C (99% identical), tropical clawed frog lin7b (95% identical), macaque LIN7C (94% identical), rabbit LIN7C (94% identical), rat Lin7c (94% identical), pig LIN7C (92% identical), Drosophila melanogaster veli (79% identical), Caenorhabditis elegans lin-7 (68% identical). Paralogues in human: LIN7B (84% identical), LIN7A (80% identical), PDZD11 (26% identical).
Diseases named in the same sentence as LIN7C in open-access papers:
LIN7C is named in the same sentence as 2 diseases in open-access papers, as found by Europe PMC text mining. Sharing a sentence is not in itself a finding about the gene and the disease. The quoted sentences say what the papers report.
oral squamous cell carcinoma (1 paper, 2020). "Down-regulation of LIN7C (lin-7 homolog C) was found to be related to oral squamous cell carcinoma (OSCC) metastasis in an early research." (PMID 33043022, 2020).
LIN7C also shares sentences with these, for which no sentence is quoted: cancer (1 paper).